IL1B (interleukin 1 beta)
Diseases named in the same sentence as IL1B in open-access papers (continued):
Sharing a sentence is not in itself a finding about the gene and the disease.
colitis (continued). "Nevertheless, using REV-ERBα –/– mice, increased NLRP3 and IL-1β expression was detected, and REV-ERBα was linked to experimental colitis through its ability to repress the expression of p65 subunit of NFkB, which subsequently leads to the suppression of NLRP3 inflammasome at the priming level." (PMID 33717162, 2021). "This follows recent reports showing that IL-1β and IL-18 production can provide protection against colitis, and supported by recent GWAS studies showing that the polymorphisms which confer hypofunctional NLRP3 phenotypes are associated with the development of IBD." (PMID 34692718, 2021). "In addition, RORα recruits the corepressor HDAC3 to NF-κB target promoters, which leads to transcriptional repression of the inflammatory genes (including IL-1β) in DSS-induced colitis mouse model." (PMID 33717162, 2021). "TNF-α, IL-6, and IL-1β are the most important cytokines involved in the pathogenesis of colitis." (PMID 33854556, 2021). "CR dose-dependently down-regulated Nlrp3, IL-1β, IL-6, Tnf-α and Ccl2 mRNA levels in colitis mice." (PMID 34393786, 2021). "A previous studies has shown inflammation could be promoted by IL-1β and stimulated the expression SIgA against the adhesion of pathogens in colonic inflammation." (PMID 34163442, 2021). "We demonstrated that olaparib improved TNBS-induced colitis in mice, reduced histological damage of the colon, diminished the number and length of the ulcers, inhibited proinflammatory cytokine production (IL-1β, IL-6), but it enhanced the level of anti-inflammatory cytokine IL-10." (PMID 34567413, 2021). "Moreover, antibody neutralization of IL-1β protected mice from Helicobacter hepaticus-triggered colitis by limiting the accumulation of granulocytes and IL-17A-producing innate lymphoid cells." (PMID 33562334, 2021). "Moreover, the therapeutic effects were further improved when the colitis mice were treated with IL-1β-primed ERCs (vs. ERC, p < 0.01)." (PMID 34090510, 2021). "There are reports that treatment with NLRP3 inhibitors can relieve colitis under DSS exposure, which might be caused by the local reduction of pro-inflammatory cytokines, including IL-1β, TNF-α, and IFN-γ." (PMID 34955826, 2021). "Moreover, miR-223 has been shown to limit intestinal inflammation by targeting NLRP3 inflammasome expression in monocytes to inhibit IL-1β production during murine colitis." (PMID 33672304, 2021). "CPT-11 could activate inflammasome NLRP3, promote caspase-1 to cleaved the precursor of IL-1β and release a large amount of mature IL-1β into colonic tissue, resulting in colitis." (PMID 34025639, 2021). "We found that IL-1β production was obviously reduced in Gsdmd-/- mice during DSS-induced colitis, and we asked whether the reduced pathological severity of Gsdmd-/- mice was due to reduced IL-1β secretion." (PMID 34721422, 2021). "Compared with the sham group, colonic pro-inflammatory cytokines, including TNF-α, IL-1β, and IL-8, were significantly increased in the colitis group, and these changes could be significantly reversed by 20 and 80 mg/kg aucuboside." (PMID 34335262, 2021). "Some animal experiments by Wang and his workmates showed that ginsenoside Rg3 could significantly ameliorate DSS-induced colitis by inhibiting the expression of pro-inflammatory cytokines (IL-1β and IL-6)." (PMID 33462754, 2021). "We found that colon mucosal Il1b expression was induced to a much higher degree in DSS-induced compared to Il10−/− colitis, and that IL-1β induced Il33 from colon fibroblasts in vivo, however IL1R signaling was not required for induction of Il33 expression during DSS." (PMID 33953267, 2021). "In addition, probiotic treatment or FMT can reduce the expression and secretion of inflammatory factors (such as IFN-γ, IL-12, TNF-α, IL-6, and IL-1β) to resist colitis by regulating STAT1, STAT4, or NF-κB signals." (PMID 33532501, 2021).
colitis (continued). "Interestingly, the mRNA and content of the pro-inflammatory cytokine IL-1β were increased by TB supplementation in this study, similar to the effects of TB supplementation in experimental colitis." (PMID 33912175, 2021). "Finally, we mechanistically connect chronic colitis-induced inflammation and miR-155-mediated changes in cardiomyocytes through IL-1β." (PMID 34543287, 2021). "Our recent in vitro and in vivo studies observed that active vitamin D prevented the host from the detrimental effects of overwhelming inflammation by downregulating pro-inflammatory responses (IL-6, TNF-α, IL-8, and IL-1β) in Salmonella-infected IECs and decreased the severity of colitis in mice." (PMID 34943999, 2021). "Then, in in vivo experiments, they showed that the intensified colitis could be ameliorated by depletion of CCR2+ inflammatory monocytes, and that overexpression of miR-223 caused blockade of IL-1β or NLRP3." (PMID 33808793, 2021). "In addition, we observed that ERCs downregulated DKK1 expression by IL-1β pre-stimulation, and IL-1β-primed ERCs attenuated the development of colitis." (PMID 34090510, 2021). "Furthermore, we found that PHLPP2−/− mice developed hypersensitivity to dextran sulfate sodium (DSS) treatment toward colitis showing activated NF-κB signaling and dramatically induced expressions of caspase-1 P20, Gasdermin N, IL-18, and IL-1β." (PMID 34394827, 2021). "However, treatment with C29, DW2009, or donepezil reduced LPS-induced colon shortening, myeloperoxidase activity, and TNF-α and IL-1β expression and increased IL-10 expression in the colon, leading to in the alleviation of colitis." (PMID 34579150, 2021). "For example, caffeic acid, tea polyphenols, salvianolic acid, and sesamol could ameliorate colitis by reducing the levels of IL-1β, IL-6, TNF-α, and other pro-inflammatory cytokines in DSS-induced models." (PMID 35059326, 2021). "LTA reduced the lipopolysaccharide (LPS)-mediated histological damage, decreased the level of TNF-α, IFN-γ, IL-6 and IL-1β and enhanced the intestinal permeability by increasing the expression of certain tight junction proteins in LPS-induced murine model of colitis." (PMID 33219923, 2021). "The data showed that the expression of miR-223 was increased in biopsies from active IBD patients and that miR-223-deficient mice exhibit exacerbated experimental DSS-colitis characterized by increased NLRP3 inflammasome activation, and elevated IL1β production in the colon." (PMID 33808793, 2021). "In a colitis model, the authors demonstrated that the loss of the ODC gene leads to pronounced induction of inflammatory cytokines including GM-CSF, TNF-α, IL-1α and IL-1β, and IFN-γ as well increased macrophage polarization towards M1." (PMID 34206987, 2021). "Consequently, IL-1β-primed ERCs exhibited an enhanced therapeutic effect in the attenuation of DSS-induced colitis." (PMID 34090510, 2021). "We firstly found that Il1b was induced over 1000-fold more in DSS compared to Il10−/− colitis." (PMID 33953267, 2021). "Considering the amount of IL-1β secreted in the distal colon of Winnie mice together with our earlier results that a small molecule inhibitor of the NLRP3 inflammasome ameliorates colitis in Winnie mice, it is possible that UTA77 also prevents NLRP3 inflammasome activation." (PMID 34497514, 2021). "We also confirmed that IL-1β-primed ERCs could ameliorate the symptoms, alleviate the pathological damages, and modulate the balance of immunocytes in colitis mice." (PMID 34090510, 2021). "IL-1β neutralization might be further tested for its ability to ameliorate HF in different preclinical models of colitis before consideration of proceeding to human clinical trials." (PMID 34543287, 2021). "To further evaluate the modulatory role of IL-1β-primed ERCs on the local immune environment, we have performed the immunohistochemical staining to analyze the intra-colon macrophage infiltration in this colitis model." (PMID 34090510, 2021).
colitis (continued). "The reduced neuropathology observed in NLRP3 KO mice following DSS-induced colitis may have resulted from lower mature IL-1β production and ensuing infiltration of fewer gut-derived T cells." (PMID 34229722, 2021). "Likewise, mice carrying the same activating mutation (Nlrp3R258W) that is responsible for increased NLRP3 activation and IL-1β levels in patients with cryoporin associated periodic syndrome (CAPS) were resistant to DSS colitis and T cell transfer colitis." (PMID 34344313, 2021). "For example, caffeic acid, tea polyphenols, salvianolic acid, and sesamol could ameliorate colitis by reducing the levels of IL-1β, IL-6, TNF-α, and other pro-inflammatory cytokines in DSS-induced colitis mice." (PMID 34867926, 2021). "As lactic acid treatment significantly decreased the level of the pro-inflammatory cytokine IL-1β, which is an inflammatory cytokine released by macrophage pyroptosis in colitis, in DSS-fed mice, we decided to explore the effect and the mechanism of lactic acid on macrophage pyroptosis." (PMID 34899735, 2021). "We found that the production of IL-1β was reduced in Gsdmd-/- mice compared to WT mice in DSS-induced colitis, so we asked whether the decreased IL-1β expression is important for the protective effect in Gsdmd-deficient mice." (PMID 34721422, 2021). "In fact, the TNBS induced colitis causes an increase in the expression of TLR4, IL-1β, and IL-8." (PMID 32183497, 2020). "By contrast, the pharmacological stimulation of A3 receptors with IB-MECA resulted effective in protecting against colitis through the reduction of inflammatory cytokine (i.e., IL-1β, IL-6, and IL-12) and chemokine (i.e., macrophage inflammatory protein (MIP)-1α and MIP-2) levels in colonic tissues." (PMID 32708507, 2020). "Moreover, CA4P exacerbated the pathological features of colitis and significantly increased proinflammatory cytokines (IL-1β, IL-6, TNF-α) and inflammatory cells (neutrophil, lymphocyte, monocyte)." (PMID 32265711, 2020). "The colon of EV-treated mice showed reduced levels of inflammatory cytokines (TNF-α, IFN-γ, IL-1β, IL-6 and iNOS) and elevated levels of an anti-inflammatory/regulatory cytokine (IL-10), compared to that of untreated mice with colitis and TSG-6-depleted EV-treated mice." (PMID 32040478, 2020). "The level of pro-inflammatory cytokines (TNFα, IL-1β and IL-6) in the blood serum, as well as IL-1β in the colon tissue of mice with colitis receiving algae extract, was lower than that in control animals, and the level of anti-inflammatory interleukin IL-10 was higher." (PMID 32486405, 2020). "Furthermore, mRNA expression of genes encoding cytokines including IL-6, IL-1β, and TNF-α, and protein expression of COX-2 and iNOS were upregulated in the colon tissue of mice with DSS-induced colitis." (PMID 32059355, 2020). "However, the single-strain cheese intake enhanced IL1β expression during DSS colitis, compared to the healthy group." (PMID 32156075, 2020). "Oral treatments with the compounds significantly suppressed TNBS-induced expressions of IL-10, in addition to TNF-α, IL-6, and IL-1β in colon tissues, indicating that an anti-colitis activity of the compounds led to the resolution phase of TNBS-induced inflammation." (PMID 31619080, 2020). "Moreover, nanoparticles derived from grapefruit are taken up by intestinal macrophages and improve experimental colitis in mice by upregulating the expression of heme oxygenase-1 (HO-1) and inhibiting the production of IL-1β and TNF-α." (PMID 32365813, 2020). "Interestingly, we found that colitis results in the upregulation of IL-1β, IFN-γ, and TNF-α mRNA transcripts and the reduced expression of tight junction proteins." (PMID 32855978, 2020). "Furthermore, the expression of pro-inflammatory cytokines, like IL-6, TNF-α and IL-1β, was decreased in a peptidoglycan-polysaccharide-induced colitis rat model." (PMID 32722619, 2020).
colitis (continued). "The severity of acute colitis in HFiD-fed mice was only slightly milder as compared with control mice, but it was accompanied with a decrease in colonic Il1b expression, suggesting lower pro-inflammatory tuning, which we had already observed in HFiD-fed healthy mice." (PMID 33339337, 2020). "In addition, it has been documented that intestinal Il-1β and Il-17A produced by ILCs play an important role in the development of Hh-induced colitis in RAG2 mice." (PMID 33255175, 2020). "We measured the gene expression of the pro-inflammatory cytokines nitric oxide synthase 2 (NOS2) and interleukin 1 β (IL-1β), as well as the anti-inflammatory interleukin-4 (IL-4) cytokine, in colonic tissues before and after induction of colitis and during recovery." (PMID 32349250, 2020). "In mice with dextran sulfate sodium (DSS) or 2,4,6-trinitrobenzenesulfonic acid-induced colitis, MaR1 reduced leukocyte infiltration, inhibited neutrophil migration, and reduced the levels of the following proinflammatory cytokines: IL-1β, TNF-α, IL-6, and INF-γ." (PMID 32751593, 2020). "Using anti-IL-1β antibodies has also been shown to improve DSS-induced colitis in rodents." (PMID 32013062, 2020). "As a derivative of coptisine, (±)-8-ADC (75, 150, and 300 mg/kg) treatment activates the transcriptional activity of X-box binding protein 1 and decreases NF-κB expression, subsequently reduces secretion of myeloperoxidase, TNF-α, IL-6 and IL-1β in the colon of DSS-induced colitis mouse." (PMID 32063999, 2020). "Furthermore, transplantation of mesenchymal stem cells pretreated with IL-1β was shown to reduce DSS-induced colitis." (PMID 33143375, 2020). "However, sinapic acid treatment also decreased the serum and colonic levels of IL-1β and IL-18, which were associated with decreased NLRP3, ASC, and caspase-1 protein levels in the colons of colitis mice." (PMID 33312339, 2020). "Furthermore, we unravel a critical role of the canonical NLRP3 inflammasome in Cg-induced IL-1β secretion and colitis, which is an important discovery on the pro-inflammatory properties of this sulfated polysaccharide for pre-clinical studies." (PMID 32894139, 2020). "Some of this evidence suggests that after colitis occurs, the production of IL-1β, IL-18, and anti-inflammatory cytokines IL-10 and TGF-β decreases in Nlrp3−/− mice, which may in turn hinder repair mechanisms and increase intestinal epithelial permeability." (PMID 33227973, 2020). "Colitis is characterized by expression of both pro-inflammatory cytokines, including tumour necrosis factor-alpha (Tnfa), interleukin 1-β (Il1b), and interleukin 17 A (Il17a), and anti-inflammatory cytokines, including interleukin 10 (Il10) and interleukin 22 (Il22)." (PMID 32042047, 2020). "Among these cytokines, IL-1β exhibits increased production in the model of DSS-induced colitis." (PMID 33192516, 2020). "Furthermore, IL-1β secreted from infiltrated neutrophils in the colonic mucosa contributes to the pathogenesis of colitis." (PMID 33192516, 2020). "Triptolide also suppressed IL-1β and IL-6 expression in mouse colitis tissue." (PMID 33240279, 2020). "Little change in colonic B cells was observed after IL-1β blockade in Fcgr2b−/− mice; however, there was a reduction in the severity of colitis and colonic neutrophil infiltration, directly implicating this pathway in detrimental immune responses driven by dysregulated FcγR signaling." (PMID 30876876, 2019). "However, treatment of DSS + CD-induced colitis mice with PWS produces a reduction in the level of IL-1β and an increase in the expression of both IL-10 and TGF-β in the colonic tissue." (PMID 31888274, 2019). "Furthermore, it has been revealed that in the inflamed mucosa of IBD, IL-1β, a key mediator of colonic inflammation initiation, has a crucial role in the pathogenesis of colitis." (PMID 31888274, 2019).
colitis (continued). "With regard to the pro-inflammatory cytokines IL-1β, IL-6, and TNFα, our results are consistent with the data obtained by others, who showed that the level of pro-inflammatory cytokines increases in animals with colitis induced by exogenous agents." (PMID 31590413, 2019). "Furthermore, these cell subsets represent the dominant source of IL-1β production, one of the dominant inflammatory cytokines in human and murine colitis." (PMID 31031776, 2019). "Interestingly, apart from toxin-induced cytotoxicity, C. difficile infection leads to the activation of a cascade of mucosal pro-inflammatory cytokines, including IFNγ, TNFα, and IL1β, that result in recurrent colitis or ileitis." (PMID 30948494, 2019). "In addition, weight loss in mice with colitis that were treated with M2 macrophage exosomes (DSS + M0-exo; DSS + IL-13-exo; DSS + IL-10-exo; and DSS + IL-1β-exo) was also alleviated." (PMID 31749791, 2019). "However, the concept of detrimental inflammasome signaling in IBD is being re-evaluated due to recent reports that IL-1β and IL-18 production can confer protection against colitis." (PMID 30873162, 2019). "In an analogy, herewith we showed that during the induction phase of DSS-induced colitis Gal-3 deficient macrophages were not able to optimally produce IL-1β upon TLR4:LPS stimulation which led to their polarization towards immunosuppressive M2 phenotype." (PMID 31336879, 2019). "Studies have shown that the thalidomide treatment reduce TNF-α, IL-6 and IL-1β production, and histological analysis showed considerable reduction in neutrophil infiltration and mucosal damage in colon homogenate of experimental colitis." (PMID 31920668, 2019). "In addition, M2b macrophage exosomes increased the percentage of Treg cells in mice with DSS-induced colitis and reduced pro-inflammatory cytokine (IL-1β, IL-6, and IL-17A) production in the colon of mice with DSS-induced colitis." (PMID 31749791, 2019). "In addition, FA-97 successfully prevented colitis by inhibiting the production of IL-1β, IL-6, TNF-α, IL-12, MIP-1α, and IL-17 in colons." (PMID 31969881, 2019). "Mice deficient in IL-1β exhibit a severe non-healing disease after DSS colitis, suggesting involvement in intestinal repair." (PMID 30876876, 2019). "Astaxanthin induced improvements of various factors in DSS colitis, including: clinical and histological parameters, mRNA expression of inflammatory cytokines (IL-1β, IL-6, TNF-α, IL-36α and IL-36γ), activation of transcription factors NF-κB and AP-1 (c-Jun), and MAPK phosphorylation." (PMID 30705514, 2019). "Indeed previous researches on experimental colitis have shown a positive correlation of TNF-α, IL-1β, and IL-6 levels in animal with colitis and the degree of colonic inflammation." (PMID 32641944, 2019). "However, the mechanisms of action of thalidomide are not yet entirely clear, its benefit has primarily been ascribed to its roles as an anti-TNF-alpha agent and reduce TNF-α, IL-6 and IL-1β production in colon homogenate of experimental colitis." (PMID 31920668, 2019). "Colon tissue from vehicle-treated mice had higher levels of TNF-α, IL-6, and IL-1β than did colon tissue from mice treated with the probiotic complex or the combination drug; the latter exerted the greatest effect on colitis (p < 0.001, p < 0.001, and p < 0.01, respectively)." (PMID 29466999, 2018). "Furthermore, this colitis was dependent on IL-1β generation since mice deficient in both TLR5 and IL-1R were protected from such induction of colitis." (PMID 30455704, 2018). "Similarly, IL-1β infiltrating cell expression increased in CD patients as well as in various experimental models of colitis." (PMID 30024891, 2018). "Development of colitis is often associated with chronic inflammation, characterized by inflammatory cellular infiltration and series of cytokines secretion, such as TNF-α, IFN-γ, IL-6, IL-1β, IL-4, and IL-10." (PMID 29538417, 2018).